CDK20 (cyclin dependent kinase 20)
Description:
Required for high-level Shh responses in the developing neural tube. Together with TBC1D32, controls the structure of the primary cilium by coordinating assembly of the ciliary membrane and axoneme, allowing GLI2 to be properly activated in response to SHH signaling (By similarity). Involved in cell growth. Activates CDK2, a kinase involved in the control of the cell cycle, by phosphorylating residue 'Thr-160'.
Synonyms: CCRK; CDCH; p42; PNQALRE
Tractability: Small molecule: a drug acting on it is in phase 2 or 3 trials; it belongs to a druggable protein family. PROTAC: ubiquitination databases record sites on it; its protein half-life has been measured; a small molecule that binds it is known.
Target class: Kinase; Enzyme; CMGC protein kinase CDK family; CMGC protein kinase group; Protein Kinase
Gene: Protein-coding gene on chromosome 9 (87,964,906 to 87,974,764, reverse strand). Ensembl gene ENSG00000156345.
Subcellular location: Nucleus; Cytoplasm; Cell projection, cilium
Subcellular location (Human Protein Atlas): Nucleoplasm; Connecting piece; End piece; Golgi apparatus; Mid piece; Principal piece
Gene Ontology:
Molecular function: protein binding; ATP binding; cyclin-dependent protein serine/threonine kinase activity; protein kinase activity; protein serine kinase activity
Biological process: regulation of cell cycle
Cellular component: nucleoplasm; cilium; cytoplasm; nucleus
Genetic constraint (gnomAD): Loss-of-function variants: 40 observed, 38.8 expected, observed/expected ratio (o/e) 1.03, 90% interval 0.8 to 1.34. The upper end of that interval is the gene's LOEUF score, 1.34, which puts it in group 5 of 6, group 1 being the genes least tolerant of losing a copy. Missense variants: 512 observed, 451.3 expected, observed/expected ratio (o/e) 1.13, 90% interval 1.05 to 1.22. Synonymous variants: 209 observed, 184.39 expected, observed/expected ratio (o/e) 1.13, 90% interval 1.01 to 1.27.
Homologues: Orthologues: chimpanzee CDK20 (99% identical), macaque CDK20 (97% identical), mouse Cdk20 (94% identical), rabbit CDK20 (94% identical), rat Cdk20 (94% identical), guinea pig CDK20 (93% identical), dog CDK20 (84% identical), zebrafish cdk20 (75% identical), Drosophila melanogaster CG6800 (36% identical). Paralogues in human: CDK3 (39% identical), CDK12 (38% identical), CDK1 (37% identical), CDK11B (37% identical), CDK13 (37% identical), CDK5 (37% identical), CDK11A (37% identical), CDK7 (37% identical), CDK2 (37% identical), CDKL5 (35% identical), CDK9 (35% identical), CDK10 (34% identical), and 14 more.
Diseases named in the same sentence as CDK20 in open-access papers:
CDK20 is named in the same sentence as 42 diseases in open-access papers, as found by Europe PMC text mining. Sharing a sentence is not in itself a finding about the gene and the disease. The quoted sentences say what the papers report.
hepatocellular carcinoma (16 papers, 2018 to 2025). A malignant tumor that arises from hepatocytes. "CDK20 inhibition was found to enhance the efficacy of immune-checkpoint blockade in hepatocellular carcinoma." (PMID 33686962, 2021). "Transcription of CDK20 (CCRK) was activated by ligand-bound androgen receptor (AR) in hepatocellular carcinoma cells (HCCs), and CDK20 in turn upregulated β-catenin signaling, which upregulated the expression of the β-catenin target gene, AR, creating a cycle that induced tumor growth." (PMID 39941813, 2025). "This includes, for instance, the identification of cyclin-dependent kinase 20 (CDK20) as a novel target in hepatocellular carcinoma and generation of potent CDK20 inhibitors using the generative chemistry platform Chemistry42 coupled with subsequent in vitro explorations." (PMID 36435816, 2022). "In hepatocellular carcinoma (HCC), the androgen receptor (AR) acts as a positive regulator of the CDK20 promoter." (PMID 39800748, 2025).
glioblastoma (10 papers, 2014 to 2025). The most malignant astrocytic tumor (WHO grade IV). "CDK20 has been functionally linked to glioblastoma where it behaves as an oncogene and contributes to increased proliferation." (PMID 38523660, 2024). "Inhibition of CDK20 significantly reduces glioblastoma growth through ciliogenesis, indicating that CDK20 is a potential therapeutic target for glioblastoma treatment." (PMID 39941813, 2025). "Depletion of CDK20 affects the proliferation of glioblastoma cells, an aggressive type of brain tumor." (PMID 39941813, 2025). "In various cancer cells, including glioblastomas, liver cancer, ovarian cancer, and colorectal cancer cells, CDK20 can activate CDK2 and control the cell cycle progression of cancer cells." (PMID 41302865, 2025). "Glioblastoma cells display deregulated, high levels of CDK20, and its depletion inhibits glioblastoma cell proliferation in a cilium-dependent manner." (PMID 38523660, 2024). "Interestingly, CILK1/ICK was found to mediate the effect of CDK20 on ciliogenesis in glioblastoma cells and it also regulates the inhibitory effect of fibroblast growth factor on cilia by interacting with FGFR3." (PMID 38523660, 2024). "In glioblastoma cells, knockdown CDK20 blocks cancer cell proliferation." (PMID 33198081, 2020). "In glioblastoma cells, CDK20 expression allows cell proliferation." (PMID 33198081, 2020). "Overexpression of CDK20 was found in glioblastoma tumor tissue and glioma cell lines compared to the normal tissue, while siRNA silencing of CDK20 inhibited growth and reduced CDK2 phosphorylation in U-373 MG and U-87 MG glioblastoma cells." (PMID 39941813, 2025).
ovarian carcinoma (7 papers, 2010 to 2025). A malignant neoplasm originating from the surface ovarian epithelium. "In ovarian carcinoma, CDK20 knockdown in cells led to G1 phase cell cycle arrest, and CDK20 overexpression caused cell proliferation in vitro and tumor growth in vivo, and is positively correlated with an advanced stage of ovarian cancer." (PMID 33198081, 2020). "CDK20 was also demonstrated to promote ovarian carcinoma cell proliferation via regulation of cyclin D1 and is a predictor of outcome in patients with ovarian carcinoma." (PMID 33198081, 2020). "CDK20 also known as CCRK, which has sequence homology to CDK7, represents a novel cell cycle-related kinase (CAK) activity, and controls cell cycle progression in various cancers including lung, colorectal, liver and ovarian cancer." (PMID 33868579, 2021). "Similarly, CDK20 also was found in ovarian carcinoma cell lines and CDK20 has no CAK activity on CDK2 but promotes cell proliferation via increases in cyclin D expression." (PMID 33198081, 2020).
breast carcinoma (5 papers, 2021 to 2025). "The results revealed that the mRNA expression of CDK7, CDK8, CDK9, CDK10, CDK12, CDK19, and CDK20 was upregulated in patients with breast cancer." (PMID 33686962, 2021). "Precisely how CDK20 functions in breast cancer remain largely unknown." (PMID 33868579, 2021). "In breast cancer, CDK1, CDK5, and CDK20 are overexpressed, while CDK2 and CDK6 are decreased, with high expression correlating with poor prognosis." (PMID 39567714, 2024). "The results showed that although the mRNA expression of CDK7, CDK8, CDK19, and CDK20 was higher in breast cancer tissues, none of these transcripts’ values reached statistical significance." (PMID 33686962, 2021).
ciliopathies (5 papers, 2021 to 2025). "Mouse Cdk20 mutants also display overly long cilia and show classic ciliopathy phenotypes, including defective Hedgehog signaling." (PMID 41385589, 2025). "Mutations in CDK20 and TBC1D32 are associated with ciliopathies and defective embryonic development resulting from the dysregulation of Hh signaling." (PMID 37545519, 2023).
glioma (5 papers, 2014 to 2025). A benign or malignant brain and spinal cord tumor that arises from glial cells (astrocytes, oligodendrocytes, ependymal cells). "In this case, knockdown of CDK20 leads to G1 phase cell cycle arrest and decreased CDK2 phosphorylation, suppressing the growth of glioma cells in vivo, implicating CDK20 as an oncogene for this type of cancer." (PMID 33198081, 2020).
liver cancer (5 papers, 2021 to 2025). An epithelial or non-epithelial malignant neoplasm that arises from the liver. "Moreover, further study revealed that CDK20 results in EZH2 (zeste homolog 2) upregulation and may be associated with poor survival in liver cancer." (PMID 33868579, 2021).
lung carcinoma (4 papers, 2021 to 2025). "CDK20 also promotes resistance to radiotherapy and chemotherapy by activating the NRF2 pathway in lung cancer." (PMID 39941813, 2025). "CDK20 modulates the KEAP1–NRF2 cytoprotective pathway and regulates tumor progression, implying that it is a potent therapeutic target for lung cancer." (PMID 33868579, 2021).
heart failure (3 papers, 2020 to 2025). Inability of the heart to pump blood at an adequate rate to meet tissue metabolic requirements. "Further investigation on this novel variant of CDK20 may yield a unique target for diagnostic markers and treatment therapies for patients with ischemic cardiac diseases and heart failure." (PMID 33198081, 2020). "Overexpression of cardiac CDK20 protects cardiomyocytes from death and prevents cardiac stress-induced heart failure." (PMID 33198081, 2020).
intraductal cribriform breast adenocarcinoma (1 paper, 2021). A ductal carcinoma in situ of the breast characterized by the presence of a cribriform architectural pattern. "Higher CDK20 expression was in turn found in both intraductal cribriform breast adenocarcinoma (fold change = 2.225) and invasive ductal and lobular carcinoma (fold change = 1.645) in TCGA." (PMID 33686962, 2021).
membranoproliferative glomerulonephritis (1 paper, 2019). Inflammation of the glomeruli characterized by deposits at the intraglomerular mesangium, resulting in thickening of the glomerular basement membrane, activation of complement, and impaired kidney function secondary to damaged glomeruli. "WES of a patient diagnosed with membranoproliferative glomerulonephritis (MPGN) identified homozygous missense mutations in a highly conserved amino acid residue of cyclin dependent kinase 20 (CDK20)." (PMID 30761277, 2019).
nephrotic syndrome (1 paper, 2020). A collection of symptoms that include severe edema, proteinuria, and hypoalbuminemia; it is indicative of renal dysfunction. "Since DLC1 is regulated by cyclic dependent kinase 20 (CDK20) and tensin-2 (TNS2), mutations in TNS2 and cyclin-dependent kinase 20 (CDK20) are also causative in some cases of nephrotic syndrome." (PMID 32708597, 2020).
osteosarcoma (1 paper, 2020). A usually aggressive malignant bone-forming mesenchymal neoplasm, predominantly affecting adolescents and young adults. "Some of these genes have been reported as biomarkers for osteosarcoma, while the role of HLA-DRA, MTIF2, MRPS7 and CDK20, should also be further systematically investigated based on actual diseased tissues or even cell lines and animal models." (PMID 32665038, 2020).
tumor (34 papers, 2015 to 2025). "Cell cycle-related kinase (CCRK) now known as CDK20 has been specifically implicated in tumor-mediated immunosuppression by induction of MDSC in response to IL-6 upregulation." (PMID 38188300, 2023). "CDK20 may also be a positive component in the Wnt signaling pathway, present in the cell to aberrantly activate β-catenin and to provoke tumor-associated cell proliferation." (PMID 33198081, 2020). "Meanwhile, on the TCGA portal, we found that CDK7, CDK8, CDK9, CDK12, CDK19, and CDK20 mRNA levels were differentially expressed in the 4 molecular tumor subtypes." (PMID 33686962, 2021). "PR−/ER− cases demonstrated frequent loss of LNX1 and SNORA80A, and gain of ZNF4, STK24 and CCDC191; gain of CDK20 was common in PR-high tumours." (PMID 34079052, 2021). "Among selected hypoxia-related transcripts, we observed two significantly upregulated transcripts (Lox and Adm), and three significantly downregulated transcripts (Cdk20, E2f6, and Ccnd1) in tumor-bearing versus vehicle mice." (PMID 32151276, 2020). "CCRK behaves as an oncogene in GBM as depleting CDK20/CCRK inhibited tumor growth." (PMID 35295905, 2022). "CDK20 has been found expressed in various human tissues, predominantly in the brain and kidney, and to a lesser extent in the liver, heart, and placenta; it is also widely expressed in cell lines originating from a variety of tumor tissues." (PMID 33198081, 2020). "The interaction of CDK20 with KEAP1, confirmed by co-immunoprecipitation of endogenous proteins in HEK293T cells, enables NRF2 activation, helping tumor cells survive therapy-induced stress." (PMID 39941813, 2025). "Among these 20 common genes, the expression levels of CDK20, AKAP7, AZIN2, LIX1L, OSCP1, and SLFN12 were upregulated, while HLF was downregulated in TC-PD-L1+ tumours (Pattern 3 and Pattern 4)." (PMID 29921949, 2018). "Interestingly, expression of CDK19 and CDK20, which did not appear to influence cell survival in the in vitro conditions used to generate the DepMap dataset, are nonetheless associated with better/worse tumor progression free survival (PFS) in multiple tumor types." (PMID 36577800, 2022). "The vast majority of genes were equally expressed in tumor and non-tumoral, control pituitary glands, including CCNL1, CCNE2, CCNB2, CCNA1, CDK18, CDK19 and CDK20." (PMID 35260162, 2022).
cancer (23 papers, 2018 to 2025). A tumor composed of atypical neoplastic, often pleomorphic cells that invade other tissues. "This study used AlphaFold to predict the structure of CDK20 (Cyclin-Dependent Kinase 20), which is involved in cell cycle regulation; its abnormal activity can lead to uncontrolled cell growth, a hallmark of cancer." (PMID 38540759, 2024). "The study indicated that the CDK20 expressed in adult cardiomyocytes is a unique splice variant that is different from those in normal cells with the capability of cell division, and that it is also distinct from cancer cells." (PMID 33198081, 2020). "Several studies have reported the overexpression of CDK20 in cancers from the brain, colon, liver, lung, and ovary." (PMID 38523660, 2024). "CDK20 upregulation in some of these cancers is clinically significant as it correlates with tumor staging, shorter patient survival, and poor prognosis." (PMID 38523660, 2024). "Overexpression of CDK20 promotes proliferation and is regarded as a tumorigenesis-related factor in many cancers." (PMID 36873930, 2023). "CDK20 is a newly identified human CDK family protein that is known to control cell cycle progression in various cancers." (PMID 33868579, 2021). "This review summarizes the new progress in studies of CDK20 and p21Cip1/Waf1 in cell growth, cell survival, and their potential implications, focusing on cancers and heart disease." (PMID 33198081, 2020). "It is thought that CDK20 is also responsible for the proliferation of other cancers such as cervical carcinoma, osteosarcoma, and colorectal carcinoma." (PMID 33198081, 2020). "CDK20 has been of particular interest in various cancer research lines because of its activating role in cell proliferation." (PMID 33198081, 2020). "This makes CDK20 a critical factor in cancer cell resistance to standard therapies." (PMID 39941813, 2025). "In conclusion, CDK20 has a driver function in various cancer-associated pathways, and even though the mechanisms of CDK20 involvement in cancer progression are not completely elucidated, the downregulation of CDK20 in cancer has a proven therapeutic potential." (PMID 39941813, 2025). "There are also reports indicating that CDK20 might involve cancer cell survival by other signaling such as via MRK/ICK signaling via phosphorylation of the essential Thr-157 in their T-loop in prostate cancer cells." (PMID 33198081, 2020). "Besides acting as a potential therapeutic cancer target, CDK20 and p21Cip1/Waf1 have also been considered targets of preventing chemotherapy resistance treatment in cancer." (PMID 33198081, 2020). "Cyclin dependent kinase 20 (CDK20) and p21Cip1/Waf1 are widely recognized as key regulators of cell cycle checkpoints controlling cell proliferation/growth and involving in developing multiple cancers." (PMID 33198081, 2020). "Pharmacological inhibition of CDK20 causes both cycling and noncycling cancer cell death." (PMID 33198081, 2020). "In addition, CDK20 was found involved in the pathogenesis of diseases, particularly in cancers." (PMID 33198081, 2020). "This research highlights the critical need for further investigation into the specific mechanisms by which CDK20 and MGMT influence cancer development and treatment to optimize therapeutic strategies and improve patient outcomes." (PMID 39767561, 2024). "Recent research has highlighted the significant role of CDK20 (cyclin-dependent kinase 20) and MGMT (O6-methylguanine-DNA-methyltransferase) in the development and treatment of various cancers." (PMID 39767561, 2024). "CDK20’s involvement in the EZH2/NF-κB, KEAP1-NRF2, and Wnt signaling pathways further underscores its critical role in cancer progression." (PMID 39767561, 2024). "Cyclin-dependent kinase 20 (CDK20) or CCRK, is a member of CDK family with strong linkage to human cancers." (PMID 30846786, 2019).
cancer (continued). "Whereas CDK19 and CDK20 are not essential in any of the cancer cell lines tested, there is a minor proportion of cell lines in which CDK8 (~ 3%), CDK10 (~ 1%), CDK12 (~ 27%) and CDK13 (~ 3%) are essential." (PMID 36577800, 2022).
heart disease (2 papers, 2020 to 2025). "Importantly, cardiac CDK20 has been linked to heart diseases." (PMID 33198081, 2020). "It is of utmost importance that the function of CDK20 and p21Cip1/Waf1 in the heart is elucidated because they can have major implications on the development of novel therapies for heart diseases, thus improving the quality of life and life expectancy for affected patients." (PMID 33198081, 2020).
CDK20 also shares sentences with these, for which no sentence is quoted: Obesity (11 papers); colorectal cancer (4); non-alcoholic steatohepatitis (4); alcoholic liver diseases (1); cervical adenocarcinoma (1); chronic myeloid leukemia (1); clear cell renal cell cancer (1); CNS tumors (1); coloboma (1); diabetes (1); Glucose intolerance (1); hepatic steatosis (1); Hyperinsulinemia (1); Insulin resistance (1); invasive ductal and lobular carcinoma (1); lactic acidosis (1); liver steatosis (1); medulloblastoma (1); melanoma (1); microphthalmia (1); ovarian tumors (1); pancreatic cancer (1); prostate carcinoma (1); renal carcinoma (1); steatosis (1); viral hepatitis (1).